XPA (XPA, DNA damage recognition and repair factor)
Diseases named in the same sentence as XPA in open-access papers (continued):
Sharing a sentence is not in itself a finding about the gene and the disease.
breast carcinoma (11 papers, 2008 to 2025). "In the case of the rs1800975 polymorphism, XPA has been shown to reduce the risk of breast cancer and esophageal cancer in the Asian population." (PMID 38892180, 2024). "Postmenopausal females with XPA rs1800975 carrying one or two A alleles have a higher breast cancer risk than those with GG genotype, consistent with reports on populations of northern Chinese and South Korean women." (PMID 27768589, 2016). "The key finding was that two polymorphisms, XRCC1 gene rs25487 and XPA gene rs1800975, might exert both independent and interactive effects on the development of breast cancer." (PMID 24642895, 2014). "We therefore in this study aimed to assess the potential interactions of seven common polymorphisms from five DNA repair genes (XRCC1, XRCC2, XRCC3, XPA and APEX1) in association with breast cancer among Han Chinese women." (PMID 24642895, 2014). "Deletion analysis of PHF2, FANCC, PTCH1 and XPA were examined in a subset of 47 early-onset (group-A: ≤ 40 years) and 59 late-onset (group-B: > 40 years) breast carcinomas using both microsatellite and exonic markers." (PMID 18990233, 2008). "On the contrary, XPA rs1800975 and XPC rs2228001 were associated with decreased breast cancer risk." (PMID 27768589, 2016). "In conclusion, our findings provide clear evidence that XRCC1 gene rs25487 and XPA gene rs1800975 might exert both independent and interactive effects on the development of breast cancer." (PMID 24642895, 2014). "Our findings provide clear evidence that XRCC1 gene rs25487 and XPA gene rs1800975 might exert both independent and interactive effects on the development of breast cancer among northern Chinese women." (PMID 24642895, 2014). "ER, HER2, E-Cad, Ki67, Molecular subtypes, XRCC1, XRCC4, 53BP1, ERCC1 and XPA were not independent prognostic factors of postoperative breast cancer metastasis (P > 0.05)." (PMID 33184404, 2020). "For tumor tissue characteristics, XPA rs1800975 and ERCC2/XPD rs50872 carriers have a high risk of breast cancer with negative expression of ER and PR." (PMID 27768589, 2016). "SRI-011381 alone did not change the expression of XPA, XPB, XPC, and XPF in the breast cancer cells." (PMID 40303493, 2025).
melanoma (11 papers, 2014 to 2026). A malignant, usually aggressive tumor composed of atypical, neoplastic melanocytes. "After transfection into A375 melanoma cells and puromycin selection, PCR sequencing of the targeted exons confirmed the generation of polyclonal XPA-mutated cell lines." (PMID 36232946, 2022). "Like XP patients, XPA-iPSCs accumulated single-nucleotide substitutions that are associated with malignant melanoma, a manifestation of XP." (PMID 27197874, 2016). "From the iPSC mutation patterns in this study, the mutation signature of XPA-iPSCs is suggested to resemble to Signature 1B, 7 or 14, which are strongly related to melanoma, while those of ATM-deficient iPSCs resemble to Signature 5 and 9, lymphoma-related signatures." (PMID 27197874, 2016). "The results of our study serve as the fundamental basis for the investigation of the immunological consequences of XPA disruption in melanoma." (PMID 36232946, 2022). "On the other side, the NER protein XPA has been proven to promote cell protective autophagy in melanoma cells treated with cisplatin, a chemotherapeutic drug." (PMID 32635505, 2020). "XPA promotes autophagy in resistant melanoma cells after cisplatin treatment through facilitating PARP1 activation." (PMID 32635505, 2020). "Relevant to melanoma, XPA is rate-limiting in the NER system for the elimination of bulky DNA lesions from ultraviolet radiation as well as platinating agents during therapy." (PMID 29581861, 2018). "We therefore used Clustered Regularly Interspaced Short Palindromic Repeats (CRISPR) and CRISPR-associated (Cas) protein 9 to target XPA, the central coordinator of NER and scaffold provider for other NER proteins, in the well-established human melanoma cell line A375." (PMID 36232946, 2022). "Additionally, chromatin-immunoprecipitation (ChIP) showed that the circadian clock protein BMAL1 transcriptionally binds to the promoter region of the human XPA gene in human melanoma cells, further supporting a direct link with the endogenous circadian clock." (PMID 29581861, 2018). "Thus, XPA knockdown sensitizes melanoma cells to cisplatin by impairment of autophagy through activation of PARP-1." (PMID 29112132, 2017). "Therefore, we used CRISPR/Cas9 to disrupt XPA in A375 melanoma cells." (PMID 36232946, 2022). "Further approaches are needed to analyse whether TAp73 directly or indirectly regulates the expression of NER components on transcript or protein level, especially in the context of XPA expression and which genome-stabilizing mechanisms rely on TAp73 expression in melanoma cells." (PMID 30206212, 2018). "When A375 human melanoma cells were treated with 6 μM cisplatin for 48 h, an increase in the level of three NER proteins, ERCC1, XPF and XPA, was seen." (PMID 29254481, 2017). "Similarly, chromosome 9 and 10, commonly deleted in these cancers, contain several important suppressor genes such as CDKN2A and PTEN in glioma; XPA, PPP6C, and CDKNA in melanoma; PTCH1 and SUFU in medulloblastoma." (PMID 41537310, 2026). "Standard chemotherapeutics, such as cisplatin, are ineffective on metastatic melanoma and we, and others, have shown that levels of a number of NER proteins in melanoma cells are elevated in response to cisplatin: ERCC1 and XPF, XPC and DDB2, XPA (this publication)." (PMID 29254481, 2017). "The possibility that ATR-dependent phosphorylation of various substrates, including XPA and/or XPC, might regulate NER exclusively during S phase specifically in melanoma cells is currently under investigation." (PMID 24416382, 2014). "We found that several HRR-associated genes, including DDB2, RAD51, BRCA1, XRCC2 and BRCA2, are overexpressed in melanoma cells compared to primary melanocyte cultures, while the expression of the NER-associated genes XPA, ERCC1 and ERCC4 showed no clear differences." (PMID 32719412, 2020).
ovarian carcinoma (10 papers, 2005 to 2024). A malignant neoplasm originating from the surface ovarian epithelium. "​Ovarian cancer had the characteristics of high familial incidence, and the results of our cohort showed that XPA and NF2 were associated with familial inheritance of ovarian cancer." (PMID 38817903, 2024). "Enhanced NER gene expression is a major cause of resistance to cisplatin and other DNA-damaging chemotherapeutic agents and over expression of the XPA gene component of NER has been associated with resistance to cisplatin in human ovarian cancer." (PMID 15882455, 2005). "Although XP genes are typically associated with the hereditary disease of the same name, XPA, XPB, and XPF have been shown to have increased expression in platinum-resistant ovarian cancer cells." (PMID 36551731, 2022). "A similar increase in expression was observed for both excision repair cross-complementing group 1 (ERCC1) and XPA in platinum-resistant ovarian cancer tissues." (PMID 36551731, 2022). "In ovarian cancer, XPA has been shown to be expressed at a high level in tumors of patients resistant to cisplatin treatment." (PMID 36496984, 2022). "Over-expression of XPA and ERCC1 mRNA has been associated with cisplatin resistance in ovarian cancer." (PMID 21696631, 2011). "In the present study, we performed a hypothesis-based association to explore the impact of SNPs in these core genes (XPA, XPC, XPG, ERCC1, ERCC2, and ERCC4) on the risk of ovarian cancer by genotyping a pool of 17 SNPs in 89 patients and 356 controls." (PMID 29669843, 2018). "While XPA is overexpressed in platinum-resistant ovarian cancer tumors, it does not seem to have a role in DNA excision activity." (PMID 36551731, 2022). "Therefore, we conducted genotyping for 17 SNPs of six NER core genes (XPA, XPC, XPG, ERCC1, ERCC2, and ERCC4) in 89 ovarian cancer cases and 356 cancer-free controls." (PMID 29669843, 2018). "Our thorough evaluation of the NER protein levels (XPA, XPC, XPF, XPG, ERCC1, and DDB2) and corresponding mRNA levels in various cisplatin-sensitive and -resistant ovarian cancer cell lines revealed that the transcript levels of various NER factors do not accurately reflect their protein levels." (PMID 21385444, 2011).
colorectal cancer (9 papers, 2015 to 2024). A primary or metastatic malignant neoplasm that affects the colon or rectum. "The enrollment of more case–control studies following the HWE principle in diverse ethnicities will help researchers to further verify the potential genetic role of the XPA rs1800975 polymorphism in the risk of lung or colorectal cancer." (PMID 32435155, 2020). "The potential effect of XPA rs1800975 on the risk of developing lung or colorectal cancer still merits the enrollment of larger well-scaled studies." (PMID 32435155, 2020). "We cannot obtain a relatively scientific conclusion regarding the potential links of XPA rs1800975 and colorectal cancer risk." (PMID 32435155, 2020). "Moreover, downregulation of XPA has been associated with decreased patient survival in colorectal cancer." (PMID 39660592, 2024). "Nevertheless, our data from FPRP analysis and another pooling analysis with only the population-based controls in the Caucasian population did not strongly support the protective role of the G allele within the XPA rs1800975 polymorphism in the risk of lung or colorectal cancer." (PMID 32435155, 2020). "In a study corresponding to colorectal cancer in the Chinese population, some NER genetic variants (XPA rs10817938 and XPC rs2607775) were illustrated to alter disease risk." (PMID 38089451, 2022). "The expression characteristics of XPA in colorectal cancer (CRC) and its influence on CRC prognosis remain elusive." (PMID 29675892, 2018). "Although XPA did not present tumor-normal differential expression in TCGA data base, one study has showed that XPA mRNA level was downregulated in 52 patients with Dukes' C colorectal cancer than matched normal tissues by TaqMan real-time quantitative PCR." (PMID 29568775, 2018). "We assessed the association between 94 single nucleotide polymorphisms (SNPs) within seven XP genes (XPA–XPG) and the colorectal cancer risk in the Polish population." (PMID 25391773, 2015). "The present retrospective cohort study aimed at investigating whether MLH1,APEX1,MUTYH,OGG1,NUDT1,XRCC5, XPA, and ERCC2 single nucleotide polymorphisms (SNPs) are associated with colorectal cancer (CRC) in Chinese population with Lynch syndrome." (PMID 29664240, 2018). "XPA expression was also evaluated in colorectal cancer patients, where, in contrast to our TGCT data, high XPA protein expression predicted longer OS." (PMID 36293346, 2022). "DNA repair protein XPA is significantly decreased in colorectal cancer tissues than in adjacent nontumor tissues." (PMID 29675892, 2018). "In summary, DNA repair protein XPA is significantly decreased in colorectal cancer tissues than adjacent nontumor tissues." (PMID 29675892, 2018). "In this study including 283 CRC patients in China, we, for the first time, elucidated that DNA repair protein XPA is significantly decreased in colorectal cancer tissues than adjacent nontumor tissues." (PMID 29675892, 2018). "In the present study, differential expression of XPA between colorectal cancer and nontumor adjacent tissues was explored." (PMID 29675892, 2018).
prostate carcinoma (5 papers, 2011 to 2022). A carcinoma that arises from epithelial cells of the prostate gland. "A significantly higher level of XPA mRNA expression was seen in prostate cancer compared to that of control." (PMID 36509750, 2022). "Consistently, XPA knockout sensitized prostate cancer cells to abiraterone and enzalutamide treatment." (PMID 36509750, 2022). "In conclusion, IDA combats abiraterone and enzalutamide resistance by reducing XPA protein level in prostate cancer." (PMID 36509750, 2022). "XPA knockout inhibited abiraterone- and enzalutamide-resistant prostate cancer cell growth both in vitro and in vivo." (PMID 36509750, 2022). "To further verify the role of XPA in abiraterone resistance, we then analyzed clinical profiles of XPA in prostate cancer using the TCGA database." (PMID 36509750, 2022). "Another example is XPA detected as significant using the discovery cohort and confirmed by the identification of two additional rare truncations (E111* and V244fs) in prostate cancer using the validation cohort." (PMID 26689913, 2015). "XPA is a novel regulator of abiraterone and enzalutamide resistance in prostate cancer." (PMID 36509750, 2022). "In this study, we found that targeting XPA overcame abiraterone and EZN resistance in prostate cancer cells." (PMID 36509750, 2022). "Furthermore, XPA is required for IDA-induced antitumor activity in abiraterone- and enzalutamide-resistant prostate cancer cells." (PMID 36509750, 2022). "XPA is a potential target for abiraterone- and EZN-resistant prostate cancer patients." (PMID 36509750, 2022).
xeroderma pigmentosum group A (5 papers, 2016 to 2024). "PARP-1 activation also occurs in neurodegenerative DNA repair disorders including xeroderma pigmentosum group A (XPA) and Cockayne syndrome group B (CSB), and treatment with specific PARP inhibitors rescues defective phenotypes in XPA mutant worms and CSB mutant mice respectively." (PMID 27465020, 2016).
esophageal cancer (4 papers, 2017 to 2024). A primary or metastatic malignant neoplasm involving the esophagus. "In addition, thanks to the automatic testing of several genetic models and subgroup analysis we found a significant association between rs1800975 SNP in XPA gene and esophageal cancer under the overdominant genetic model that may be interesting enough for further testing." (PMID 29246109, 2017). "For example, most of the genes on the trunk of sample ESCC12 (CCND1, EGFR, APC, TGFBR2, XPC, XPA, FLI1, and NUMA1) have been identified and initially reported on the esophageal cancer." (PMID 30540749, 2018).
germ cell tumor (4 papers, 2020 to 2022). A benign or malignant, gonadal or extragonadal neoplasm that originates from germ cells. "A recent report correlated XPA expression levels in germ cell tumors to an aberrant cisplatin response and identified it as an independent prognostic biomarker for poor patient outcomes." (PMID 34065298, 2021). "While others have clearly indicated the significance of XPA phosphorylation on its stability, increased XPA levels in cisplatin resistant germ cell tumor cells could not be linked to its phosphorylation status." (PMID 34065298, 2021).
glioma (4 papers, 2003 to 2026). A benign or malignant brain and spinal cord tumor that arises from glial cells (astrocytes, oligodendrocytes, ependymal cells). "RT‐qPCR and Western blotting methods were performed to determine the expression of PAICS, ERCC1 and XPA genes in glioma tissues." (PMID 34173716, 2021).
testicular cancer (4 papers, 2015 to 2022). A primary or metastatic malignant neoplasm that affects the testis. "XPA is expressed at low levels in testicular cancer, which is generally very responsive to cisplatin, thereby providing further correlative evidence for the importance of NER in cisplatin resistance." (PMID 36496984, 2022). "Subsequently, the lower DNA repair capacity of testicular cancer cell lines was confirmed by measuring the ability of cell extracts to remove platinum-DNA adducts, and the addition of XPA protein to the cell extracts was sufficient to restore in vitro DNA repair capacity." (PMID 30208165, 2018). "Specifically, low constitutive NER capacity and low levels of XPA, XPF and ERCC1 (NER proteins) have been reported in cisplatin-hypersensitive testicular cancer cells compared to other tumor types resistant to cisplatin." (PMID 27626685, 2016). "It has been known that intra-strand lesions, the primary type of DNA damage caused by CDDP are repaired by the nucleotide excision repair (NER) pathway and exquisite sensitivity to CDDP is observed in testicular cancer, which often presents with low expression of NER proteins, such as XPA and ERCC1." (PMID 26338199, 2015).
Xeroderma pigmentosum complementation group A (4 papers, 2012 to 2024). Xeroderma pigmentosum complementation group A (XPA) is a severe form of xeroderma pigmentosum (XP; see this term), a rare photodermatosis predisposing to skin cancers. "UVB-induced CPDs are repaired by nucleotide repair mechanisms (NER) mediated by xeroderma pigmentosum complementation group A (XPA)." (PMID 39770934, 2024). "Such proteins are tDNA damage-binding protein 1 (DDB1), ERCC2, Xeroderma pigmentosum complementation group A (XPA), and xeroderma pigmentosum complementation group C (XPC)." (PMID 37206523, 2023). "These eQTLs are significantly associated with 4 genes, including ADGRB2 (adhesion G protein-coupled receptor B2), WASF3 (WAS protein family member 3), SPEF2 (sperm flagellar 2), and XPA (xeroderma pigmentosum complementation group A)." (PMID 31039743, 2019).
bladder cancer (3 papers, 2011 to 2024). "XPA is also repressed in bladder cancer, in which it appears to increase the incidence of chromosome aberrations and promote carcinogenesis." (PMID 30451877, 2018). "This is in agreement with previous studies showing that XPA depletion increases phosphorylation of H2AX in glioblastoma and bladder cancer." (PMID 39001501, 2024). "The effect of valproic acid (VPA) treatment on transcription of XPC and XPA genes in both HTB4 and HTB9 bladder cancer cells." (PMID 21507255, 2011).
Cockayne syndrome (3 papers, 2010 to 2022). A multisystem condition characterized by short stature, a characteristic facial appearance, premature aging, photosensitivity, progressive neurological dysfunction, and intellectual deficit. "Loss of NEIL1, Cockayne’s syndrome-B (CSB) and XPA in mice reduces expansion, bolstering the idea that removal of oxidative DNA damage causes instability." (PMID 26247199, 2015). "Therefore we sought to investigate the role of NER factors Xeroderma Pigmentosum A (XPA), XPB and XPD in oxidative DNA damage-repair by subjecting lymphoblastoid cells from patients suffering from XP-A, XP-D and XP-B with Cockayne Syndrome to hydrogen peroxide (H2O2)." (PMID 21176161, 2010).